STAR (steroidogenic acute regulatory protein)
Diseases named in the same sentence as STAR in open-access papers (continued):
Sharing a sentence is not in itself a finding about the gene and the disease.
adenovirus infection (1 paper, 2012). "StAR gene was introduced into primary rat aortic endothelial cells by adenovirus infection." (PMID 23170972, 2012). "However, the extent of increase is reduced when StAR is overexpressed by adenovirus infection." (PMID 23170972, 2012).
adrenal tumors (1 paper, 2016). "Overall, immunohistochemical analysis revealed higher expression of StAR in adrenal tumors with mutations in PRKACA, GNAS, and PRKAR1A than in wild-type tumors, which exhibited lower expression of StAR." (PMID 27606678, 2016).
atherosclerosis (1 paper, 2022). A disease characterized by the build-up of fatty material and calcium deposition in the arterial wall resulting in partial or complete occlusion of the arterial lumen. "RXR, StAR, SREBP2, and HMGCR expression in endothelial cells contributed to dysregulated lipid metabolism and exacerbated atherosclerosis progression." (PMID 35681743, 2022).
Autoimmunity (1 paper, 2020). The occurrence of an immune reaction against the organism's own cells or tissues. "It is, therefore, possible that mutations in STAR causing even a mild reduction in steroidogenesis could promote a breakdown of tolerance to adrenocortical antigens, thus facilitating the onset of autoimmunity." (PMID 33243158, 2020).
depression (1 paper, 2026). "Behavioral and reproductive assessments included depression-like behavior tests, sexual behavior, sperm quality, testicular histopathology, steroidogenesis proteins (AR, CYP11A1, StAR), and apoptosis markers (Hsp70, caspase-3, caspase-9)." (PMID 41598271, 2026).
embryonal carcinoma (1 paper, 2025). A non-seminomatous malignant germ cell tumor characterized by the presence of large germ cells with abundant cytoplasm resembling epithelial cells, geographic necrosis, high mitotic activity, and pseudoglandular and pseudopapillary structures formation. "Expression of genes involved in general steroid biosynthesis (STAR, POMC, CYP11A1, FDX1) and the aromatase-coding gene CYP19A1 was the highest in embryonal carcinomas." (PMID 40011822, 2025).
endometritis (1 paper, 2021). An acute or chronic, usually bacterial infectious process affecting the endometrium. "Although it is difficult to explain this finding, however we assume that the effect on GDF9, StAR, and FSHr expression is associated with clinical endometritis rather than the sub-clinical endometritis." (PMID 33969045, 2021).
endothelial dysfunction (1 paper, 2012). In vascular diseases, endothelial dysfunction is a systemic pathological state of the endothelium (the inner lining of blood vessels) and can be broadly defined as an imbalance between vasodilating and vasoconstricting substances produced by (or acting on) the endothelium. "Overall our findings provided a strong support for StAR being as one of the key regulators for lipid metabolism and a protective molecule for endothelial dysfunctions in aortic endothelium." (PMID 23170972, 2012). "Our results using siRNAs to inhibit StAR expression confirmed a positive role for StAR in endothelial dysfunction." (PMID 23170972, 2012). "StAR can ameliorate endothelial dysfunction induced by PA via reducing the intracellular lipid levels." (PMID 23170972, 2012). "Taken together, these results indicate that StAR plays a protective role in PA-induced endothelial dysfunction via regulating intracellular lipid metabolism." (PMID 23170972, 2012). "Taken together, the role of StAR overexpression in inhibiting inflammatory response and NO bioavailability in the cellular model of endothelial dysfunction might result from decreased lipid levels in RAECs." (PMID 23170972, 2012). "Based on our previous results, we hypothesized that StAR plays a protective role in endothelial dysfunction induced by FFA via regulating lipid metabolism." (PMID 23170972, 2012). "However, the role of StAR in endothelial dysfunction remains unclear to date." (PMID 23170972, 2012).
hypercortisolism (1 paper, 2024). "In summary, we identified that the TP receptor regulates adrenal corticosterone homeostasis through the p38/14‐3‐3γ/p‐StAR signaling pathway, suggesting that intervention of the TP‐mediated pathway may be a promising strategy for the treatment of hypercortisolism." (PMID 38460156, 2024).
hypogonadotropic hypogonadism (1 paper, 2021). Abnormal ovarian or testicular function due to insufficient hormonal stimulation from the hypothalamic-pituitary axis. "For example, boys with X-linked adrenal hypoplasia (NR0B1/DAX-1) are at risk of developing hypogonadotropic hypogonadism in adolescence, whereas there is a potential risk of long-term sex steroid insufficiency or hypofertility with partial defects in STAR or CYP11A1/P450scc." (PMID 34258490, 2021).
hypothyroidism (1 paper, 2022). Abnormally low levels of thyroid hormone. "Hypothyroidism is linked to a decrease in StAR gene expression, according to certain studies." (PMID 35871495, 2022). "This study is the first to show a link between hypothyroidism and PCOS by looking at the testosterone hormone and the key gene of StAR, as well as oxidants and antioxidants." (PMID 35871495, 2022).
infertility disorder (1 paper, 2022). Inability to conceive for at least one year after trying and having unprotected sex. "This study provides evidence that an increase in CatSper, StAR, 3β-HSD, and CYP20A1 and downregulation of STAT3, COX-2, and associated signaling pathways can provide an effective strategy to prevent CDDP-induced reproductive toxicity and infertility disorders." (PMID 36290786, 2022).
Leydig cell tumor (1 paper, 2020). A sex cord-stromal tumor occurring in the testis and rarely in the ovary. "In line with this, it was previously shown in a mouse Leydig cell tumor model that c-Jun binds to activator protein-1 (AP-1) motif in the promoter region of StAR and increases both StAR transcription and P4 synthesis." (PMID 33042587, 2020).
liposarcoma (1 paper, 2017). A usually painless malignant tumor that arises from adipose tissue. "Estrogen-like chemicals acted similarly in human liposarcoma cells (SW 872), e.g., mono-(2-ethylhexyl) phthalate affected mitochondrial translocated protein (TSPO), located in the mitochondrial membrane and coupled with steroidogenic acute regulatory protein (StAR)." (PMID 28315012, 2017).
malaria (1 paper, 2019). Malaria is a serious and sometimes fatal disease caused by a parasite that commonly infects a certain type of mosquito which feeds on humans. "However, our design contains seven controls where the true curve is vertical: in iRefSeq and in the Baruzzo sets, especially malaria, there is no doubt that the highly covered unannotated introns of STAR and HISAT2 are false positives, despite their high coverage." (PMID 31345161, 2019).
metastatic tumors (1 paper, 2025). "IHC analysis further confirmed the low expression of STAR in metastatic tumors." (PMID 40098624, 2025). "However, despite the overall low levels, STAR expression in metastatic tumors was still higher in post-chemotherapy samples compared to pre-chemotherapy samples." (PMID 40098624, 2025). "However, STAR expression was lower in metastatic tumors, suggesting spatial or functional heterogeneity depending on the tumor context." (PMID 40098624, 2025).
non-alcoholic fatty liver disease (1 paper, 2021). "Previous work has demonstrated that STAR overexpression in high-fat diet-induced non-alcoholic fatty liver disease (NAFLD) in mice decreased intracellular DAG levels, indicating a protective role for STAR in NAFLD through a reduction in DAG levels." (PMID 33670702, 2021).
non-small cell lung carcinoma (1 paper, 2024). A group of at least three distinct histological types of lung cancer, including non-small cell squamous cell carcinoma, adenocarcinoma, and large cell carcinoma. "Referring to a prior study on non-small cell lung cancer regarding in situ production of progesterone, we further observed whether the steroidogenic enzymes (StAR, CYP11A1, HSD3B2) are present and functional in PDAC cells." (PMID 38424455, 2024).
oligodendroglioma (1 paper, 2023). A well-differentiated (WHO grade II), diffusely infiltrating neuroglial tumor, typically located in the cerebral hemispheres. "Study revealed the presence of steroidogenic acute regulatory protein (StAR) in oligodendrogliomas (ODs), particularly in low-grade tumors and suggested that the neurosteroidgenesis mechanism mediated by StAR may play a role in the growth of ODs." (PMID 38116383, 2023).
ovarian diseases (1 paper, 2024). "Conversely, several downregulated genes crucial for folliculogenesis were also found to be linked to ovarian diseases, namely, genes for sex hormone biosynthesis such as STAR, CYP17A1, and ALDH1A1, along with genes required for follicle development, such as INHA." (PMID 38126810, 2024).
overnutrition (1 paper, 2021). An imbalanced nutritional status resulting from excessive intake of nutrients. "Bull fetuses exposed to maternal overnutrition experienced a decrease in expression of steroidogenic acute regulatory protein (StAR), hydroxysteroid 17-Beta dehydrogenase 3 (HSD17B3), IGF1, IGF2, and IGF1 receptor (IGF1R), genes involved in testes development and steroidogenesis." (PMID 34438674, 2021).
Swyer syndrome (1 paper, 2024). "Considering the risk of malignancy in gonads in patients with Swyer syndrome, the data suggest that some pathogenic variants (FTLHL17, DAX-1, DHH R124Q, del at 17q24.3) may be associated with a higher risk and some (STAR, STARD8, MAP3K1) with a lower risk of tumorigenesis." (PMID 38337479, 2024).
Testicular atrophy (1 paper, 2022). Wasting (atrophy) of the testicle (the male gonad) manifested by a decrease in size and potentially by a loss of fertility. "Concomitant treatment with kinetin, however, prevented the CIS-induced testicular atrophy, as shown by counteracting oxidative stress and preserving sperm quality, testosterone level, and StAR protein expression." (PMID 35624727, 2022).
vitamin D deficiency (1 paper, 2024). A nutritional condition produced by a deficiency of VITAMIN D in the diet, insufficient production of vitamin D in the skin, inadequate absorption of vitamin D from the diet, or abnormal conversion of vitamin D to its bioactive metabolites. "Enzymes like StAR, 17β-HSD, 3β-HSD, CYP11A1, and CYP17A1 are crucial for androgen synthesis in Leydig cells, with calcitriol shown to up-regulate CYP11A1 and CYP17A1 and increase 3β-HSD levels; conversely, vitamin D deficiency can decrease StAR, 3β-HSD, CYP11A1, and CYP17A1 expression in the testes." (PMID 38698459, 2024).
tumor (34 papers, 2008 to 2025). "Spatial transcriptomics suggest that STAR + cells are spatially proximal to CAFs, but they showed stronger spatial association with tumor cells compared to CAFs." (PMID 40098624, 2025). "Only one tumor with a GNAS mutation showed low expression of StAR, possibility because of the procedures used to prepare the formalin-fixed paraffin embedded (FFPE) samples." (PMID 27606678, 2016). "The second novel subtype are STAR+ cancer-associated fibroblasts, mainly present in tumor lesions." (PMID 39796089, 2024). "The literature also indicates that TPTE, INMT, and STAR are differentially expressed in tumours and may be associated with prognosis." (PMID 36818393, 2023). "Only one tumor with low expression of StAR harbored the GNAS mutation R201H." (PMID 27606678, 2016). "Reduced LH-induced steroid synthesis and higher expression of StAR protein were seen in rat primary LCs and tumor LC lines preincubated with the mitogen-activated protein kinase (MEK) inhibitors U0126 and PD98059." (PMID 40332028, 2025). "In summary, these findings suggest that STAR + cells represent a distinct CAF subtype and are closely associated with tumor cells." (PMID 40098624, 2025). "WNT7A-FZD6/FZD3+LRP6/LRP5, critical components of the canonical Wnt signaling pathway, were exclusively expressed in STAR + cells and tumor cells." (PMID 40098624, 2025). "In pre-chemotherapy samples, the proportions of tumor cells, STAR + cells, and T lymphocytes were higher in the sensitive group, while CAFs and macrophages were more abundant in the resistant group." (PMID 40098624, 2025). "We observed significant differences in ligand-receptor pairs (LRPs) between STAR + cells and tumor cells in the sensitive and resistant groups." (PMID 40098624, 2025). "While chemotherapy reduced tumor cell numbers, STAR + cells became more prevalent in both primary tumors and bulk RNA-seq analyses." (PMID 40098624, 2025). "This relationship among STAR + cells, Wnt signaling, and tumor cells has also been reported in other studies." (PMID 40098624, 2025). "Our findings demonstrate that STAR + cells are distinct from both stromal and tumor cell populations." (PMID 40098624, 2025). "To distinguish STAR + cells from tumor cells, we performed inferCNV analysis, which showed that STAR + cells exhibited low CNV levels, similar to CAFs and smooth muscle cells (SMCs), whereas tumor cells displayed high CNV levels indicative of malignancy." (PMID 40098624, 2025). "Spatial transcriptomics and IF revealed that STAR + cells were closely localized to tumor cells, suggesting potential cell-cell interactions." (PMID 40098624, 2025). "By integrating multiple omics analyses of SOC with real-world clinical data, we aim to elucidate the role of STAR + cells and their interactions with tumor cells in mediating responses to platinum-based chemotherapy." (PMID 40098624, 2025). "The interaction between STAR + cells and tumor cells highlight the complexity of the TME in SOC and underscores the need to identify specific CAF subtypes that impact treatment outcomes." (PMID 40098624, 2025). "While these findings indicate that StAR acts as a tumor promoter in ER+ BC, its differential expression in malignant and non-malignant breast tissues designates this cholesterol transporter as a new diagnostic marker." (PMID 39201419, 2024). "Overexpression of STAR in MA-10 mouse tumor Leydig cells was found to induce steroidogenesis to a similar extent as cAMP, and introduction of STAR into non-steroidogenic COS-1 cells transfected with the CYP11A1 system increased steroidogenesis 6-fold." (PMID 36292972, 2022). "To study the potential roles of constitutive STAR, we developed STAR KO MA-10 mouse tumor Leydig cells." (PMID 33670702, 2021).
tumor (continued). "Oxidative damage is linked to the disruption in the mitochondria of mouse (MA-10) tumor leydig cells, and reduce the expression of steroidogenic acute regulatory protein (StAR), which in turn inhibits steroidogenesis." (PMID 32414135, 2020). "In contrary, in tumor mouse Leydig cell line (mLTC-1), StAR activity was increased while LHR expression was significantly reduced." (PMID 32180008, 2020). "In tumor MA-10 Leydig cells, treated with different concentrations of Roundup, the expression of aromatase and steroidogenic acute regulatory protein (StAR) also decreased." (PMID 30857531, 2019). "ACAs with high expression of StAR had significantly smaller tumor volume (P < 0.001) and higher urinary cortisol per tumor volume (P = 0.032) than those with low expression of StAR." (PMID 27606678, 2016). "ACAs having high expression of StAR exhibited higher cortisol secretion per tumor volume (P = 0.032) and smaller tumor volume (P < 0.001) than those with low expression." (PMID 27606678, 2016). "Tumors with high expression of StAR also had significantly higher 24-h urinary free cortisol levels per tumor volume than those with low expression did [44.0 (26.6–82.9) vs. 35.3 (17.1–58.1) μg/cm3/day; P = 0.032]." (PMID 27606678, 2016). "After adjusting for age and sex, the tumor volume of ACAs with high expression of StAR was significantly smaller than that of ACAs with low expression [8.3 (5.9–10.7) vs. 13.2 (9.0–20.3) cm3, P < 0.001]." (PMID 27606678, 2016). "Further communication analysis indicated that STAR + cells may suppress WNT signaling in tumor cells, contributing to improved chemotherapy responses." (PMID 40098624, 2025). "Moreover, analysis of tumor specimens from SOC patients receiving platinum-based chemotherapy at our center confirmed that STAR expression was significantly higher in the sensitive group (N = 24) compared to the resistant group (N = 20)." (PMID 40098624, 2025). "This paradoxical enrichment may reflect STAR + cells’ role in creating a microenvironment less favorable for tumor survival during chemotherapy." (PMID 40098624, 2025). "Additionally, we found that Wnt signaling transmitted unidirectionally from STAR + cells to tumor cells via paracrine signaling." (PMID 40098624, 2025). "Additionally, deconvolution of scRNA-seq annotations into TCGA and GTEX bulk RNA-seq data revealed that STAR + cells are predominantly present in normal tissues, with significantly lower enrichment in tumor tissues compared to tumor cells." (PMID 40098624, 2025). "Thirdly, the small clinical sample size and focus on SOC limit our ability to assess the correlation between STAR + cells and clinical features, and further exploration of STAR + cells in other tumor types is needed, with ongoing sample collection and collaboration to validate these findings." (PMID 40098624, 2025). "The key role of StAR in cholesterol transport and steroid hormone synthesis has been widely confirmed.For example, testosterone was significantly decreased in star knockout (KO) mice and star knockout MA-10 cells (tumor stromal cells in mice)." (PMID 40760016, 2025). "Hence, it is conceivable that StAR acts as a tumor promoter and/or oncogene in hormone-sensitive BCs." (PMID 36614200, 2023). "This is consistent with previous findings that showed that inhibition of PLC by U73122 in R2C rat tumor Leydig cells, which constitutively produce steroids and have high basal levels of STAR, was inhibitory to steroid production and decreased STAR protein levels." (PMID 33670702, 2021). "However, in chemotherapy-sensitive patients, Wnt signaling was suppressed, indicating that STAR + cells may enhance chemotherapy efficacy by inhibiting Wnt signaling in tumor cells." (PMID 40098624, 2025).